CD9 (CD9 molecule)
Diseases named in the same sentence as CD9 in open-access papers (continued):
Sharing a sentence is not in itself a finding about the gene and the disease.
infection (continued). "To substantiate the role of CD9 in HPV infection of human epithelial cells we tested the effect of CD9 protein knockdown on HPV16 PsVs infection rate of HeLa, HaCaT and primary keratinocytes (NHEK)." (PMID 32385608, 2020). "Consistent with this, J774.2 macrophages overexpressing CD9 showed significantly reduced MNGC formation on infection." (PMID 32253503, 2020). "It will be of interest to determine the effect of CD9 or CD81 on MNGC formation during infection with B. pseudomallei T6SS-5 and VgrG5 mutants in future studies." (PMID 33087788, 2020). "We found that both overexpression and loss of the tetraspanin decreased infection rates in cells with low endogenous CD9 levels, while reduction of CD9 expression in keratinocytes that exhibit high-CD9 protein amounts, led to an increase of infection." (PMID 32385608, 2020). "These experiments confirmed that an increase of CD9 in significantly impairs HPV16 PsVs infection in a dose-dependent manner." (PMID 32385608, 2020). "In the context of host–pathogen interaction, CD9-enriched microdomains have been described as important host cell factors in infections by various viruses." (PMID 32385608, 2020). "Tetraspanin crowds have also been documented for CD9 during the infection of coronaviruses and influenza viruses, where they colocalize with the respective receptor molecules and pseudoviral particles." (PMID 32535702, 2020). "A mouse macrophage cell line derived from a CD9 null mouse and a corresponding WT control were examined for their susceptibility to MNGC formation in response to infection with both strains of B. thailandensis." (PMID 32253503, 2020). "More specifically, a low CD9 expression level supports infection as well as ADAM17 sheddase activity and the ADAM17-mediated ERK signalling pathway." (PMID 32385608, 2020). "Current data suggest that the tetraspanin CD9 plays an important role in HPV16 pseudovirus (PsVs) infection of HeLa cells." (PMID 32385608, 2020). "A significant decrease in expression of CD9 was observed 3 h after infection of J774.2 macrophages with B. thailandensis CDC272 compared with uninfected cells." (PMID 32253503, 2020). "For instance, CD9 and its related tetraspanin, CD81, are localized in the growing tips of virus buds and involved in the infection cycle, and are directly implicated in generating membrane curvature." (PMID 32231207, 2020). "Surprisingly, depletion of CD9 decreased the infection rate in HeLa cell line and primary keratinocytes (NHEK), while in HaCaT cells the outcome was the opposite." (PMID 32385608, 2020). "Knockdown of CD63 displayed a reduction of infection by more than 50% and CD9 knockdown resulted in a strong inhibition of about 90%, which was comparable to results obtained by CD151 siRNAs." (PMID 30279342, 2018). "A significant reduction of infection by nearly 90% after CD9 depletion makes this tetraspanin an interesting target of investigation for future HPV research." (PMID 30279342, 2018). "Tspan microdomains, especially CD81 and CD9 enriched microdomains, are preferred IAV and CoV entry sites as they are required for fusion of viral and host cell membranes in pathogenic infections by both viruses." (PMID 29887866, 2018). "Upon infection, cell activation would induce migration of CD9+ pDCs to the periphery, allowing the secretion of inflammatory cytokines at the infection site." (PMID 29875769, 2018). "Together, these results emphasize the role of different tetraspanins in HPV infection and uncover the importance of CD9 for infection of HeLa cells." (PMID 30279342, 2018). "In contrast, Nlrp3−/−, Casp1/11−/−, and Asc−/− mice had diminished numbers of activated CD8+ CD9+ T cells at 2 and 4 weeks that were totally abolished at 10 weeks of infection." (PMID 28740491, 2017). "Prior to infection, uninfected HCs and MDMs are similar and both have the characteristic CD9 (tetraspanin) intracellular compartment found typically in macrophages." (PMID 25623930, 2015).
infection (continued). "The second infection quickly produced mature bone marrow plasma cells (intracellular Ighi, CD138hi, CD9+, B220−), compared to primary infection; which generates a very large population of immature splenic plasma cells (B220+)." (PMID 19121080, 2009). "This differential ability of CD81 and CD9 to support infection opened the way to investigating CD81 domains important for infection using CD9/CD81 chimeras." (PMID 18389082, 2008). "Again, because the transfection efficiency in HepG2-A16 cells is low, the ability of CD9[81B] to support infection was more evident in HepG2-A16 cells stably expressing this chimera." (PMID 18389082, 2008). "A chimera in which a CD81/CD9 sequence switch was made just before the beginning of the D helix (CD81ABC-9DE) was as efficient as CD81 in supporting infection by P. yoelii sporozoites when expressed in HepG2-A16 cells." (PMID 18389082, 2008). "In contrast, our results indicate that the A–B region of CD81 on a CD9 backbone is sufficient to allow infection of hepatocytic cells by P. yoelii sporozoites." (PMID 18389082, 2008). "To take into account the decrease of bacterial adhesion 2 h after infection, we quantified CD9 labeling intensity below bacterial colonies and normalized each value with the respective intensity of the DAPI staining, which was used as a proxy of the colony size." (PMID 41290585, 2025). "We confirmed that Alix and CD9 proteins were downregulated following the infection." (PMID 40572291, 2025). "We found that the inhibitor could reduce CHIKV infection, and CD9 is also implicated in efficient CHIKV entry and infection." (PMID 36298757, 2022). "In addition, CD9 only enhanced infection of the CHIKV ECSA genotype, which is highly dependent on CD81." (PMID 35612284, 2022). "Currently, there is no functional report on CD9 in immune defence against pathogenic infection in teleosts." (PMID 33597018, 2021). "The CD9 null macrophages did not appear to be significantly more susceptible to infection with B. thailandensis, indicating that the ablation of CD9 affected cell fusion directly." (PMID 32253503, 2020). "Likewise, during influenza A virus (IAV) and coronavirus (CoV) entry, CD9 mediates the close proximity of a protease and the virus enabling the cleavage of viral proteins which is a precondition for infection." (PMID 32385608, 2020). "Differences in endogenous CD9 expression levels might explain these contradictory results and support our conclusions drawn from our infection data." (PMID 32385608, 2020). "To test whether additional tetraspanins are involved in HPV16 infection, we applied a pseudovirus (PsV) infection assay, depleting either CD9 or CD81." (PMID 30279342, 2018). "Interestingly, infection of cells with VSV, which is known to be infectious and pathogenic in humans, also led to the downregulation of CD9, CD81, CD151 and EGFR." (PMID 29121670, 2017). "As in HepG2-A16 cells, CD81ccg9 and CD9[81B] partially restored infection." (PMID 18389082, 2008). "Furthermore, a construct where CD9 LEL was exchanged with CD81 LEL (CD9LEL81) was also able to support infection to the same extent as CD81, pointing out the importance of CD81 LEL." (PMID 18389082, 2008). "However, in combination with CD9 interference, no additive effects were observed, demonstrating association of these proteins during infection." (PMID 41105917, 2025). "MA10 infection induced six down-regulated (Pllp, Malat1, Myrf, Mag, Ptgds, Ugt8a) and two upregulated DEGs (Sgk1, Mbp), while Aβ pathology resulted in one down-regulated (Hmgb1) and ten up-regulated DEGs (Apoe, B2m, Clu, Cstd, Gfap, Psen1, Pllp, Cst7, Cd9, Plp1)." (PMID 41497643, 2025). "However, HIV-1 entry and infection can also be inhibited by tetraspanin protein blockages, such as CD9 and CD81, and CD81-mediated inhibition of viral entry could indicate the specificity of exosomes in different cell types." (PMID 33348699, 2020).
infection (continued). "Indeed, the reciprocal chimera CD81ccg9 supported P. yoelii sporozoite infection after transient transfection in HepG2-A16 cells, showing that CD81 A and B helices in a CD9 backbone are sufficient to confer HepG2-A16 cells the ability to support infection by P. yoelii sporozoites." (PMID 18389082, 2008). "Indeed, a chimera in which the end of the A helix and the B helix of CD9 were substituted by the 21 corresponding residues of CD81 (CD9[81B]: VVDDDANNAKAVVKTFHETLD) could support infection by P. yoelii sporozoites to the same extent as CD81ccg9." (PMID 18389082, 2008). "However, analyses of clinical SARS-CoV-2 isolates for their entry into cells reflecting in vivo infection environments, taking into account the cells in which CD9 is expressed, may be necessary to assess the importance of TEM-associated S proteolysis in natural infection and disease." (PMID 40872854, 2025). "Upon infection of PFA-treated cells with wild type meningococci, some TMS containing endogenous CD9 still developed at the interface with bacteria, although much less numerous and shorter than in living cells." (PMID 41290585, 2025). "The Golgi/early endosome associated adaptor protein AP1γ1 or the extracellular vesicle (EV) marker CD9 were absent in those viral fractions, suggesting that the presence of Rab27a is not due to contamination with cytosolic material or increased general release of EVs caused by infection." (PMID 39213446, 2024). "TDEVs were collected 24 h following infection and expression of AliX, TSG101 and CD9 were determined by immunoblot analysis." (PMID 39763667, 2024). "The expression levels of co-receptors CCR5, CD9, and CD81 were measured before and after infection with HIV." (PMID 37404829, 2023). "Compelling evidence indicates that the large extracellular loop (LEL) of mast cell-expressed TET proteins [Cluster of differentiation (CDs), such as CD9, CD63, CD81, CD82, CD151] plays a key role in the route of pathogens infection." (PMID 35310653, 2022). "Both tetraspanin CD9 and TMPRSS2 facilitate MERS coronavirus entry and a robust infection of mouse lungs in vivo." (PMID 34394121, 2021). "Our results imply that a low CD9 level supports ADAM17-mediated ERK activation and consequently HPV16 entry and infection." (PMID 32385608, 2020). "We also used flow cytometry to investigate the early changes in the cell surface expression of these proteins and tetraspanins CD9 and CD81 following infection." (PMID 32253503, 2020). "In the present study, we demonstrate the CD9-regulated modulation of HPV16 entry and infection of human epithelial cells." (PMID 32385608, 2020). "Tetraspanins of CD9 and CD63 were readily detectable in serum exosomes isolated at various time points post infection." (PMID 33396228, 2020). "Pre-treatment of J774.2 macrophages with GST-EC2s corresponding to CD9, CD63, and CD81 significantly suppressed MNGC formation on infection with both E264 and CDC272 strain of B. thailandensis." (PMID 32253503, 2020). "A significant enhancement of MNGC formation following treatment of J774.2 and RAW264.7 cells with anti-CD9 and anti-CD81 mAb prior to infection with B. thailandensis was observed." (PMID 32253503, 2020). "For example, a correlation between HIV-1 infection and acetylcholine-esterase, CD9 and CD63 exosome surface protein levels is observed in different models of infection, and increased protein levels are correlated with decreased HIV-1 infectivity." (PMID 30702421, 2019). "In this study, the general requirements of the tetraspanins CD9, CD63, CD81, and CD151 in infections by the most oncogenic HPV type, HPV16, were tested as previously investigated for HCMV." (PMID 30279342, 2018). "Our experiments with siRNA-mediated knockdown of CD9 and CD81 in HeLa cells highlighted the importance of both tetraspanins in HPV16-mediated infection." (PMID 30279342, 2018). "Infection with HCMV TB40 and HSV-1 downmodulated the tetraspanins CD81, CD151, and CD9, as well as EGFR." (PMID 29121670, 2017).
infection (continued). "Here we report that the scaffolding tetraspanin protein CD9 links the receptor for MERS-CoV to a membrane fusion-activating protease called TMPRSS2, forming a complex that promotes rapid and efficient infection." (PMID 28759649, 2017). "All cells positive for infection showed >86% cell surface expression of the marker protein (CD24, SSEA4, HLA-1 and CD9) by flow cytometry." (PMID 22536330, 2012). "The CD9/CD81 chimeras containing CD81 B helix but in which the C helix was that of CD9 (CD81ccg9 and CD9[81B]) had a reduced ability to support infection by P. yoelii sporozoites as compared to WT CD81." (PMID 18389082, 2008). "Our results are in agreement with a research work, who reported a decrease in ALIX and CD9 proteins in ZIKV-infected HUVEC-CLR-1730 cells, whereas in the exosomal fraction, both proteins showed an increase in expression during infection, similar to what was observed in this study." (PMID 40572291, 2025). "Similarly, it was previously shown that the treatment of cells with antibodies specific for the Tspans CD9, CD63, and CD81 reduced the infection by the coronavirus MHV and SARS-CoV, MERS-CoV, and HCoV-229E pseudovirus transductions in susceptible cells." (PMID 40872854, 2025). "Finally, we also present evidence that CD9/CD81/CD63+ EVs, including LC3+ EVs subset, represents a novel cell-free mechanism for dengue virus dissemination following infection of DCs." (PMID 38863700, 2024). "Indeed, as the CD63, CD81, and CD9 expressions in HIV-1-infected T cells were enhanced for up to 24 h post infection, infectious exosomes displayed higher CD81 and CD9." (PMID 34769038, 2021). "CD9 knockdown and overexpression produced similar patterns in the entry of HIV-1 and may be critical in the infection of macrophages." (PMID 34769038, 2021). "The interaction between CD9 and TMPRSS2 favors the entry and infection of MERS in murine lungs." (PMID 34394121, 2021). "To test whether endogenous CD9 expression levels influence infection rates in HeLa, HaCaT and NHEK cells, we initially compared endogenous CD9 protein amounts in cell lysates using quantitative analysis of Western blot bands." (PMID 32385608, 2020). "A significant enhancement of MNGC formation was observed with CD9 null infected macrophages, although these cells did not appear to show any increase in overall infection." (PMID 32253503, 2020). "Moreover and similarly to our comparative infection analyses in different cells, opposing effects on ERK activation upon CD9 depletion were observed depending on the cell line under study." (PMID 32385608, 2020). "After infection for 48 hours, more than 90% of the HaCaT cells were determined to be infected by observing GFP expression using a fluorescent microscope, and the CD9-GFP fusion protein was mainly located in the plasma membrane of HaCaT cells infected by Ad-CD9." (PMID 24147081, 2013). "Furthermore, 800C and UFH were also effective during infection of corneal and intestinal epithelial cell lines, demonstrating the importance of both CD9 and HSPGs but not α5β1 integrin during staphylococcal adherence to a range of epithelial cell types." (PMID 37486132, 2023). "Interestingly, CD9-targeting siRNAs caused a significant reduction of HPV and HCMV infections, whereas the C-terminal peptide had no or only a minor inhibitory effect." (PMID 30279342, 2018). "Therefore, we set out to determine whether, and to what extent, MERS-CoV utilizes CD9 and TMPRSS2 during in vivo infection." (PMID 28759649, 2017). "Our initial data, using CD9×81 and CD9LEL81 chimeras, indicated that CD81 SEL could be replaced with that of CD9 without affecting the ability to support P. yoelii sporozoites infection." (PMID 18389082, 2008). "In contrast, hCD9, CD9A-81BCDE and CD9[81A] did not restore infection." (PMID 18389082, 2008).
infection (continued). "It is important to note that no CD9 and flotiline-1 containing vesicles could be observed in non-infected cells in the investigated time frame, indicating a massive increase in EV release upon infection." (PMID 35163191, 2022). "Therefore, we propose that CD9 might regulate the local distribution of the protease ADAM17 and its EGFR-activating substrates, which then influences the organization of the HPV16 entry receptor platform and eventually infection." (PMID 32385608, 2020). "In contrast to the case of LC3, we did not detect significant binding of M2 with the tetraspanin CD9, a protein that was previously shown to be incorporated into IAV virions and supposedly plays a functional role during the infection process." (PMID 34494547, 2021). "All three tetraspanins—CD9, CD63, and CD81—were present in BEVs irrespective of infection or treatment status." (PMID 33036231, 2020). "Hereby, both a particularly high (HaCaT) and the absence of CD9 protein (CD9-siRNA depleted HeLa and NHEK) seemed to have a negative effect on the infection rate." (PMID 32385608, 2020). "Moreover, coexpression of CD81 and CD9 led to similarly low infection rates with this Asian genotpye as observed in Lunet cells lacking CD81 and CD9 or Lunet cells expressing CD9 only." (PMID 35612284, 2022). "In conclusion, these data show downregulation of CD9, CD81, CD151, and EGFR upon infection with two herpesviruses, two orthopoxviruses and a negative strand RNA virus, suggesting that the reduction of cell surface expression of these molecules is common upon infection." (PMID 29121670, 2017).
bacterial infections (10 papers, 2015 to 2025). "In infectious diseases, CD9(+) sEVs have been shown to participate in the immune response to viral and bacterial infections." (PMID 37371093, 2023). "In the context of bacterial infection, CD9 influences epithelial cell adherence of Neisseria meningitidis likely by facilitating specific receptor-adhesin engagement within the TEM." (PMID 30356731, 2018). "Remission of tuberculosis infection could be ascertained by the expression of CD9, an exosome marker, one of the highly expressed proteins in the recovery phase of bacterial infection cohort." (PMID 37831367, 2024). "CD9 is a crucial regulator of cell adhesion in the immune system and plays important physiological roles in hematopoiesis, blood coagulation or viral and bacterial infections." (PMID 37007105, 2023). "This set comprises a number of well characterised ISGs including Mx, viperin, IRF1 and CD9 amongst others that are strongly up-regulated by the virus, while fold changes after bacterial infection are much lower and reflect the reduced magnitude of the IFN response triggered in this context." (PMID 26487553, 2015). "Additionally, EVs from severe patients isolated by CD9+ immunocapture and mS1-EVs trapping showed increased amounts of IFITM3, an antiviral response protein previously associated with EVs in other viral and bacterial infections." (PMID 39569406, 2024). "Angiopoietin 4 (ANGP4), CD9, and immunoglobulin E (IgE) were increased and LFA3, IL5, and CD45RB were among the most decreased proteins in bacterial infection." (PMID 37831367, 2024).
adenocarcinoma (9 papers, 2012 to 2025). A common cancer characterized by the presence of malignant glandular cells. "Moreover, CD9 has been recently reported as a prognostic factor in adenocarcinoma of the lung, colon, breast, pancreas, prostate and SCC of the esophagus and oral cavity." (PMID 23128478, 2013).